SIRT6 (sirtuin 6)
Diseases named in the same sentence as SIRT6 in open-access papers (continued):
Sharing a sentence is not in itself a finding about the gene and the disease.
osteosarcoma (continued). "Therefore, this study evaluated the role and effect of SIRT6 expression on osteosarcoma by investigating the expression of SIRT6 in human osteosarcomas and assessing the role of SIRT6 in resistance to the treatment of doxorubicin in conjunction with the role of SIRT6 on the repair of DNA damage." (PMID 33198792, 2020). "However, there have been limited studies on the roles of SIRT6 in osteosarcoma." (PMID 33198792, 2020). "Whether Sirt6 is regulated by NFκB in this system remains to be explored, however, global profiling of p65 binding sites (by ChIP-seq) in TNFα-induced human osteosarcoma U-2 OS cells and TNFα-induced or poly(I:C) stimulated Detroit 562 cells did not identify SIRT6 as a NFκB/p65 target gene." (PMID 30886604, 2019). "SIRT6 activates extracellular signal‐regulated kinase 1/2 (ERK1/2) in non‐small cell lung carcinoma and osteosarcoma to drive metastatic spread via MMP9 upregulation." (PMID 35686673, 2022). "SIRT1, SIRT2, SIRT6 and SIRT7 proteins are mainly localized in the nucleus or cytoplasm and are more likely to play important roles in the development of osteosarcoma." (PMID 36344502, 2022). "Previous reports have shown that SIRT6 and SIRT7 proteins were elevated in osteosarcoma cells, and they promoted the migration and invasion of osteosarcoma cells by different mechanisms." (PMID 36344502, 2022). "Therefore, SIRT6 may function as a prognostic factor and a drug target for osteosarcoma patients." (PMID 34671398, 2021). "We evaluated the expression of CSNK2A1 and phosphorylated SIRT6 in the 37 osteosarcoma patients and investigated the effects of CSNK2A1 and the phosphorylation of SIRT6 on Ser338 on resistance to the anti-cancer effects of doxorubicin." (PMID 34359939, 2021). "Multivariable analyses showed tumor size (OS; P = 0.023, RFS; P = 0.018), distant metastasis (OS; P = 0.008, RFS; P = 0.050), and SIRT6 expression (OS; P = 0.001, RFS; P < 0.001) as independent prognostic indicators of osteosarcoma patients." (PMID 33198792, 2020). "Upon treatment with doxorubicin, overexpression of SIRT6 attenuates doxorubicin-mediated increase of apoptosis in U2OS and KHOS/NP osteosarcoma cells." (PMID 33198792, 2020). "Knock-down of SIRT6 significantly inhibited the invasiveness of SaOS2 and MG63 osteosarcoma cells by regulating the ERK1/2-MMP9 pathway." (PMID 30524965, 2018). "In addition, the cytotoxic effect of doxorubicin was attenuated with the overexpression of SIRT6 in U2OS and KHOS/NP osteosarcoma cells." (PMID 33198792, 2020). "Furthermore, co-treatment of KU-55,933 or the PARP inhibitor olaparib with doxorubicin synergistically inhibited the proliferation of SIRT6-overexpressing U2OS and KHOS/NP osteosarcoma cells." (PMID 33198792, 2020). "Therefore, a combination of inhibition of the SIRT6/SIRT6-mediated DNA damage repair pathway with conventional genotoxic anti-cancer therapies might be a new therapeutic stratagem for the poor prognostic group of osteosarcomas which have high expression of SIRT6." (PMID 33198792, 2020). "Therefore, blocking CSNK2A1 might be helpful in achieving therapeutic efficacy in osteosarcoma highly expressing CSNK2A1 and/or SIRT6." (PMID 34359939, 2021). "However, in this study, despite the prognostic significance of SIRT6 on the survival of osteosarcoma patients, the regulation of expression of SIRT6 did not significantly influence the proliferation of osteosarcoma cells." (PMID 33198792, 2020). "Similarly, SIRT6 was involved in the invasiveness but not the proliferation of osteosarcoma cells." (PMID 30524965, 2018). "At a dose of 0.05 μM doxorubicin, the knock-down or overexpression of SIRT6 did not influence on the proliferation of U2OS and KHOS/NP osteosarcoma cells." (PMID 33198792, 2020).
colorectal cancer (14 papers, 2019 to 2026). A primary or metastatic malignant neoplasm that affects the colon or rectum. "Studies in mice have shown that the loss of SIRT6 promotes the development of colorectal cancer and pancreatic cancer." (PMID 38891773, 2024). "SIRT6 deficiency occurs in several human cancers, particularly in pancreatic and colorectal cancer cells." (PMID 32905943, 2020). "The reason for this dual role is not well understood, one reason might be the complexity of the SIRT6 target proteins but also both diversity and the high mutation frequency of different colorectal cancers." (PMID 32905943, 2020). "In conclusion, our study reveals that SIRT6 plays a crucial role in regulating mitochondrial function and mitophagy in colorectal cancer." (PMID 41362737, 2026). "SIRT6 displays a complex role in colorectal cancer (CRC), functioning in both tumor-suppressive and tumor-promoting capacities depending on cellular and microenvironmental contexts." (PMID 41463311, 2025). "To investigate the role of SIRT6 in the anoikis process of colorectal cancer cells, we cultured RKO cells in suspension and assessed the expression of SIRT6." (PMID 38891773, 2024). "Here, we demonstrate that the histone deacetylase sirtuin 6 (SIRT6) plays a pivotal role in conferring anoikis resistance to colorectal cancer (CRC) cells." (PMID 38891773, 2024). "For instance, SIRT6 was shown to be lowly expressed in colorectal cancer stem cells, and its overexpression suppressed the cell proliferation, colony formation, and induced G0/G1 phase arrest in colorectal cancer stem cells via regulating CDC25A." (PMID 35251169, 2022). "SIRT6 was observed decreased in colorectal cancer tissue compared with tumor adjacent and a similar result was also showed by the online database." (PMID 35715817, 2022). "SIRT6 gene is deleted in 29 % of colorectal cancer cell lines, however, SIRT6 overexpression has also shown to correlate with poor prognosis and worse overall survivals." (PMID 32905943, 2020). "Further, SIRT6 and TFAM were overexpressed or knocked down in HCT116 cells, and scratch assays and EDU cell proliferation assays demonstrated that SIRT6 inhibits both the migration and proliferation of colorectal cancer cells, while TFAM promotes these processes." (PMID 41362737, 2026). "Depletion of the Sirt6 gene promotes the in situ development of colorectal cancer." (PMID 38891773, 2024). "In conclusion, the results demonstrated that SIRT6 inhibits TFAM, leading to mitochondrial dysfunction and inducing mitophagy, ultimately suppressing colorectal cancer growth, which were validated in vivo using a mouse xenograft tumor model." (PMID 41362737, 2026). "Taken together, it provided strong evidence that SIRT6 and TFAM play critical roles in the development and progression of colorectal cancer." (PMID 41362737, 2026). "In cervical cancer HDAC1, HDAC10, SIRT6, SIRT7 are always present; whist in colorectal cancer is HDAC10, SIRT6, SIRT7." (PMID 30691229, 2019). "This study aims to investigate whether and how SIRT6 induces mitochondrial dysfunction through the regulation of TFAM, leading to mitophagy, and consequently inhibiting colorectal cancer growth." (PMID 41362737, 2026). "It proposes that SIRT6 regulates TFAM, leading to mitochondrial dysfunction and the induction of mitophagy, which suppresses tumor progression and may provide a potential therapeutic strategy for targeting colorectal cancer." (PMID 41362737, 2026). "Our research aims to clarify the core role of SIRT6 in metabolic regulation in colorectal cancer, uncover its anti-cancer mechanisms, identifying TFAM as a promising therapeutic target and provide theoretical support for developing targeted therapeutic strategies based on SIRT6." (PMID 41362737, 2026).
progeria (14 papers, 2011 to 2024). "SIRT6 has been a focal point of aging research as progeria-like phenotypes have been associated with SIRT6 deficiency." (PMID 38421832, 2024). "Sirt6 knock-out mice, in which the gene encoding Sirt6 has been disrupted, exhibit a severe progeria or premature aging syndrome, characterized by spinal curvature, greying of the fur, lymphopenia and low levels of blood glucose." (PMID 34062897, 2021). "SIRT6 was shown to extend lifespan in mammals, while deficiency of SIRT6 was associated with progeria, an accelerated aging disorder." (PMID 33855020, 2021). "SIRT6-deficent mice developed, after 2 weeks of life, a progeroid syndrome associated with decreased lymphocyte counts in thymus and spleen." (PMID 30515162, 2018). "Loss of Sirt6 leads to a progeria-like phenotype in mice, but the target of SIRT6 action has been elusive." (PMID 21738489, 2011). "Finally, we tested the progeria causing gene, Lmna, which falls into the “inverse” category of genes that are repressed in Sirt6 knockout cells." (PMID 21738489, 2011). "In particular, SIRT6 deacetylase activity was associated with redox homeostasis/oxidative stress in human mesenchymal stem cells, suggesting that this activity may regulate longevity and progeria." (PMID 35769600, 2022). "Sirtuin 6 (SIRT6) is one of the few genes known to be involved in both longevity and progeria (Hutchinson-Gilford syndrome), a genetic disease that resembles accelerated aging (premature aging; Liao and Kennedy, 2016)." (PMID 35769600, 2022). "Given that progeria cells exhibit deficiencies in ATM and SIRT6 function, the authors investigated the possibility of using chloroquine to improve aging phenotypes in vitro and in vivo." (PMID 32046343, 2020). "Relevantly, chloroquine treatment of progeria cells activated Atm, stabilized Sirt6, reduced DNA damage, inhibited glycolysis, and ameliorated senescence." (PMID 32046343, 2020). "SIRT6 knockout mice show a progeria phenotype accompanied by sterile inflammation, an excess of cell senescence markers, stem cell exhaustion, and LINE‐1 transcription, as SIRT6 normally represses the latter." (PMID 32918364, 2020). "Specifically, Atm-Kap-1 signaling is compromised, and SIRT6 protein level and deacetylase activity are reduced in progeria cells." (PMID 29717979, 2018). "The fundamental role of Sirt6 in restoring DNA damage was initially postulated by researchers claiming that mouse cells with Sirt6 depletion exhibit increased sensitivity to DNA-damage agents, stalled proliferation, genomic instability and a progeroid syndrome." (PMID 37497437, 2023). "Here we showed that Atm is significantly downregulated, which explains the reduced SIRT6, delayed DDR, and metabolic shift in progeria cells and mice." (PMID 29717979, 2018). "On the other hand, mice lacking the SIRT6 gene showed characteristics of progeria in their phenotype." (PMID 35769600, 2022). "Unfortunately, overexpression of SIRT6 is not sufficient to rescue progeria cell dysfunction, thus limiting the usefulness of potential SIRT6-based therapeutic interventions." (PMID 27803806, 2016).
skin cancer (14 papers, 2017 to 2025). "SIRT6 exerts context-dependent roles in skin cancer, acting as both an oncogenic factor and a tumor suppressor." (PMID 41463311, 2025). "For example, SIRT6 is shown to be a driver gene in the skin cancer by promoting survival and proliferation." (PMID 33995674, 2021). "As a consequence, SIRT6 expression is upregulated in human skin squamous cell carcinoma, the second most common type of skin cancer." (PMID 32789493, 2020). "These seemingly opposing functions of SIRT6 in two types of skin cancers may be explained by differences in cell types or context, as previously reviewed." (PMID 32789493, 2020). "The role of SIRT6 in the development of skin cancer is still debatable." (PMID 29556059, 2018). "Interestingly, SIRT6 has been suggested to be an oncogene in keratinocyte-derived skin cancers." (PMID 29234488, 2017). "However, some studies suggest an oncogenic role of SIRT6 in skin cancer, squamous cell carcinoma, and acute myeloid leukemia 16-20, therefore the identification of SIRT6 modulators would be crucial for elucidating the pleiotropic effects of SIRT6 in cancer biology, as well as for cancer therapy." (PMID 32483423, 2020). "Yet, the role of SIRT6 as a tumor suppressor is challenged by the fact that SIRT6 promotes COX-2 expression and acts as an oncogene in skin cancer, suggesting a greater complexity to its role in epithelial carcinogenesis." (PMID 27659520, 2017).
diffuse large B-cell lymphoma (13 papers, 2020 to 2025). "Among these, the activation of the PI3K/Akt pathway by SIRT6 has been identified as a central pro-survival mechanism that enhances tumor growth and drug resistance in diffuse large B-cell lymphoma." (PMID 41425553, 2025). "SIRT6 has shown activity in cellular chemoresistance, however its blockade is related to increased sensitivity to chemotherapy and cellular apoptosis in diffuse large B-cell lymphomas." (PMID 36230534, 2022). "However, high levels of SIRT6 were observed in diffuse large B-cell lymphoma, and its overexpression promoted the metastasizing capacity of tumor cells and drug resistance of diffuse large B-cell lymphoma by mediating PI3K/Akt signaling." (PMID 35251169, 2022). "However, SIRT6 was found to be overexpressed in diffuse large B-cell lymphoma and promote the proliferation and invasion of tumor cells via mediating PI3K/Akt signaling." (PMID 35251169, 2022). "Similarly, the inhibition of SIRT6 sensitized diffuse large B-cell lymphoma cells on doxorubicin or bendamustine by suppressing the DNA damage repair pathway." (PMID 34359939, 2021). "This project aimed to explore the expression and functions of Sirt6 in diffuse large B-cell lymphoma (DLBCL), especially with regards to the regulatory role of OSS_128167, a novel small molecular inhibitor targeting Sirt6." (PMID 32711549, 2020). "Moreover, OSS-128167, a novel SIRT6-specific inhibitor which can decrease cell viability in primary diffuse large B-cell lymphoma (DLBCL), exerts anti-tumor activity in DLBCL cells." (PMID 35915188, 2022).
pulmonary fibrosis (13 papers, 2015 to 2026). Chronic progressive interstitial lung disorder characterized by the replacement of the lung tissue by connective tissue, leading to progressive dyspnea, respiratory failure, or right heart failure. "Lung-targeted Sirt6 delivery via injection of adeno-associated virus-Sirt6 attenuates bleomycin-induced pulmonary fibrosis." (PMID 32308644, 2020). "In summary, existing studies support the feasibility of clinical trials and treatment strategies targeting SIRT3 and SIRT6, providing a theoretical basis for the further development of Sirtuin-targeted therapies for pulmonary fibrosis." (PMID 40241794, 2025). "The attractiveness of Sirt6 as a therapeutic target had been reported in the conditions of cardiac fibrosis, renal fibrosis, and idiopathic pulmonary fibrosis." (PMID 38789630, 2024). "In the context of pulmonary fibrosis, SIRT6 has been found to inhibit bleomycin-induced injury in alveolar epithelial cells both in vitro and in mice." (PMID 38294557, 2024). "Consistent with the anti-fibrotic notion, we also found that Sirt6 overexpression inhibited lung fibrosis, as evidenced by diminished synthesis and secretion of fibrotic factors and ECM, and EMT-like cell behaviors." (PMID 28977842, 2017). "Overall, these findings indicated that AAV-mediated lung-targeted delivery of Sirt6 alleviated pulmonary fibrosis." (PMID 28977842, 2017). "In addition to Sirt3, other members of the sirtuin family, such as Sirt1 and Sirt6, have demonstrated anti-pulmonary fibrosis effects through the inhibition of cellular senescence." (PMID 39062010, 2024). "SIRT6 prevents pulmonary fibrosis by inhibiting pulmonary epithelial to mesenchymal transition." (PMID 36172184, 2022). "Among these Sirtuins, Sirt1, Sirt3, Sirt6, and Sirt7 have been well studied in pulmonary fibrosis." (PMID 34925016, 2021). "In a model of idiopathic pulmonary fibrosis, SIRT6 inhibited epithelial-to-mesenchymal transition." (PMID 33198792, 2020). "SIRT6 inhibits pulmonary fibrosis by inactivating the TGFβ1/Smad3 signaling pathway." (PMID 32308644, 2020). "Especially, SIRT6 is protective for various human diseases such as diabetes mellitus, degenerative neural disease, hepatic ischemic reperfusion injury, idiopathic pulmonary fibrosis, and muscular atrophy." (PMID 30524965, 2018). "However, there is also a controversial report that SIRT6 inhibits EMT in a model of pulmonary fibrosis." (PMID 30524965, 2018). "Overall, our findings unravel that Sirt6 acts as a key modulator in epithelial to mesenchymal transition process, suggesting Sirt6 may be an attractive potential therapeutic target for idiopathic pulmonary fibrosis." (PMID 28977842, 2017). "This article reviews the complex molecular mechanisms of the poorly studied SIRT3, SIRT6, and SIRT7 subtypes in lung fibrosis and the latest research progress in targeting them to treat lung fibrosis." (PMID 40241794, 2025). "This review focuses on the role of SIRT3, SIRT6, and SIRT7 in fibrotic diseases, analyzes their molecular regulatory mechanisms in pulmonary fibrosis, and summarizes the latest research progress for the therapy of IPF using SIRT3, SIRT6, and SIRT7 as targets." (PMID 40241794, 2025). "It has been confirmed that SIRT1, SIRT2, SIRT3, SIRT6 and SIRT7 significantly inhibit the development of lung fibrosis." (PMID 40241794, 2025). "This article reviews the role of SIRT3, SIRT6 and SIRT7 in lung fibrosis, which are relatively understudied in the Sirtuins family." (PMID 40241794, 2025). "Therefore, we speculated that inhibition of EMT by Sirt6 may contribute to eased lung fibrosis." (PMID 28977842, 2017). "In the present study, we aimed to investigate the role of Sirt6 in EMT process and EMT-related pulmonary fibrosis in both TGF-β1-induced A549 cells and bleomycin-induced experimental model." (PMID 28977842, 2017). "However, whether Sirt6 inhibits idiopathic pulmonary fibrosis remains elusive." (PMID 28977842, 2017).
pulmonary fibrosis (continued). "In summary, targeting the SIRT6-PPARα-mediated lipolysis and the TGF-β/SIRT7/FOXO4-regulated glutamine metabolic pathway may be a potential strategy for the treatment of pulmonary fibrosis and related diseases." (PMID 40241794, 2025). "In particular, the specific activation or inhibition of SIRT3, SIRT6, and SIRT7 may open up new directions for the treatment of pulmonary fibrosis." (PMID 40241794, 2025). "However, compared with cardiovascular and liver fibrosis, studies on Sirtuins in pulmonary fibrosis are still relatively rare, especially those on SIRT3, SIRT6 and SIRT7." (PMID 40241794, 2025).